MMP2 (matrix metallopeptidase 2)
Diseases named in the same sentence as MMP2 in open-access papers (continued):
Sharing a sentence is not in itself a finding about the gene and the disease.
aneurysm (continued). "Treatment with 17 β-estradiol did, however, result in reduced levels of two well-established molecular markers of aneurysm pathology, matrix metalloproteinase-2 (Mmp2) and matrix metalloproteinase-9 (Mmp9), in male Marfan mice." (PMID 37686377, 2023). "MMP-2 is the primary metalloproteinase in minor aneurysms, whereas MMP-9 is involved in late aneurysm development." (PMID 35745168, 2022). "In fact, during aneurysm formation, there is an increased number of macrophages secreting MMP-2 and -9, which are mainly located at the adventitial–medial junction." (PMID 33573220, 2021). "At the same time, MMP-2, neutrophil gelatinase-associated lipocalin (NGAL) and MMP-9 are expressed in the aneurysm wall and are involved in aneurysm development and expansion." (PMID 34439968, 2021). "The administration of doxycycline markedly prolonged MFS mice lifespan, delaying aneurysm rupture, possibly as a result of the inhibition of the MMP-2 and MMP-9 production and the subsequent reduction in aortic elastic fiber fragmentation." (PMID 34572356, 2021). "This indicates that a higher percentage of Pro-MMP-2 is activated in the aneurysm's anterior part, suggesting increased proteolysis there." (PMID 33029391, 2020). "In another study, DPP4 inhibition decreased the formation of aneurysm, elastin degradation, expression of MMP2 and -9, gelatinolytic activity, aortic apoptotic signal and macrophage infiltration in a mouse model, with similar results shown for GLP-1." (PMID 31971988, 2020). "Physiologically, an aneurysm wall has decreased elastin and increased collagen in its structure, due to the degradation of elastin, mainly by MMP-2 and MMP-9." (PMID 33419373, 2020). "Elevated levels of MMP-9 and MMP-2 are responsible for the formation and size of aneurysms, as they contribute to the degradation of elastin." (PMID 33419373, 2020). "MMP-2 is synthesized by smooth muscle cells and has been reported as a primary factor in aneurysm etiology." (PMID 33419373, 2020). "Some studies have also suggested that upregulation of MMP-2 in vascular smooth muscle cells plays an important role in MFS aneurysm development and progression." (PMID 30765726, 2019). "Raised levels of MMP-2 within 72 h of aneurysm formation, followed by a rapid return to baseline levels would suggest a role for MMP-2 in early thoracic aneurysm formation only." (PMID 31390798, 2019). "Induced activation and increased active MMP-2 are known to occur through rising wall shear stress and excessive angiotensin 2 levels in the aneurysm amongst others." (PMID 30794673, 2019). "A larger amount of MMP-2 is activated in aTAA than in control aortic tissue–a factor that seems to be a central process in aneurysm development." (PMID 30794673, 2019). "Nevertheless, there were significant differences between aneurysms < 5.5 cm and aneurysms > 5.5 cm in Pro-MMP-2 and total MMP-2 levels, and our regression analysis revealed linear relationships among the overall aneurysm group with aneurysms < 5.5.cm." (PMID 30794673, 2019). "Our protein level results further confirm a significant increase in the amount of active MMP-2 in aneurysm of the ascending aorta, as other groups have reported." (PMID 30794673, 2019). "Both aneurysm groups showed increased MMP2 activity relative to the SHAM group by week 1 and week 3, and maintained moderate expression thereafter." (PMID 29889909, 2018). "This in vitro study showed a possible link between increased Hcy levels and activation of MMP-2 and haemostatic factors in thin sections of an aneurysm." (PMID 30643799, 2018). "MMP-9 and MMP-2, which degrade the extracellular matrix, work in concert to form AAA, and both MMP-9 and MMP-2 knockout mice are resistant to aneurysm development." (PMID 29348704, 2017). "We have subsequently shown that doxycycline, which prevents release of active TGF-β through inhibition of MMP-2, delays aneurysm formation and rupture in murine models of MFS." (PMID 29040313, 2017).
aneurysm (continued). "It has been reported that MMPs synthesis and activity are increased in rat and human aneurysm tissue, especially MMP2 and MMP9, which can degrade elastin, resulting in less flexibility and loss of the integrity of the vessel walls." (PMID 28164126, 2017). "Animal models analyzing aneurysm progression reported that MMP-2 plays an important role in pathological ECM remodeling in aneurysmatic aortic tissue." (PMID 27802285, 2016). "This aneurysm showed more infiltration of macrophages and neovascularization in the aortic wall, more upregulation of MMP2 and MMP9 expression in the media, but less elastin content, endothelial recovery and a lower SMC content." (PMID 23844207, 2013). "Immunofluorescence showed that during aneurysm initiation MMP-2 and MMP-9 were distributed in SMCs, and in situ hybridization indicated that they were transcribed by SMCs." (PMID 24023941, 2013). "In the mouse genetic model, whereas either MMP-2 or MMP-9 deficiency is resistant to aneurysm formation, disruption of TIMP-1, an MMP-9 inhibitor, leads to exaggerated aneurysm growth." (PMID 22187650, 2012). "Specifically MMP-2 and MMP-9 have been implicated in the pathogenesis of aneurysm due to their capability to degrade elastin and increased expression levels in the aneurysm tissue and the plasma of patients." (PMID 22187650, 2012). "In patients with abdominal aortic aneurysm, doxycycline treatment for one week prior to the repair surgery resulted in decreased MMP-9 and MMP-2 in the wall of the aneurysms." (PMID 15667660, 2005). "Importantly, the downregulation of angiogenic and matrix-degrading genes such as VEGF, MMP-2, MMP-9, HMGB1, and NF-κB p65 further supports its role in mitigating ECM destabilization and inflammatory amplification—hallmark events in aneurysm pathogenesis." (PMID 40868841, 2025). "Biomarkers of ECM remodeling, such as matrix metalloproteinases (MMPs), particularly MMP-2 and MMP-9, and tissue inhibitors of metalloproteinases (TIMPs), have been implicated in aneurysm growth and rupture." (PMID 39301423, 2024). "Theoretically, as the lesion progresses in the late stages, inflammatory cytokines and MMP2/9 induced smooth muscle cells apoptosis, collagens fibre degradation and neovascularisation, which are key factors in the late‐stage development of aneurysms, such as aneurysm rupture and aortic dissection." (PMID 39601144, 2024). "We examined the mRNA levels of Mmp2 and Mmp9 in the aneurysm tissue." (PMID 38881898, 2024). "Increased levels of MMP-9 and MMP-2 are responsible for aneurysm formation." (PMID 37175712, 2023). "Taken together, higher MLDGS score may represent higher expression of IL1B, TLR4, VEGFA and MMP2, and lower expression of NOS3, implying inferior vascular stability at the molecular level and high risk of aneurysm rupture and CVS onset." (PMID 36844725, 2023). "The EARLY model provides clues that MMP-2 dysregulation in SMC may commence at an early stage of aneurysm development, although a profile of MMP-2 secretion over a wider range of time-points is necessary." (PMID 35326494, 2022). "Although the reduction in MMP-2 activity seen at day 28 in the aneurysm wall may reflect reduced inflammation and/or oxidative stress at an earlier timepoint." (PMID 35203568, 2022). "Additionally, in rat aneurysm cells, (Matrix Metallopeptidase 2) MMP2 and (Matrix Metallopeptidase 9) MMP9 are involved in aortic aneurysm proliferation and migration." (PMID 34997174, 2022). "Moreover, MMP-2 and -9 inhibitors reduced aneurysm growth and albuminuria in experimental and human studies." (PMID 33573220, 2021). "In addition, both flow jet angle and AAo diameter were significantly associated with elevated levels of matrix metallo-proteinase 2 (MMP-2), a protein implicated in vascular remodeling and aneurysm formation." (PMID 33842561, 2021). "Interestingly, aneurysms with more pronounced MMP‐2 and MMP‐9 expression show more extensive ECM remodelling and decreased compliance." (PMID 33847905, 2021).
aneurysm (continued). "Interestingly, increased concentrations of MMP-2, -3, and -9 have been found within the aneurysm human tissue, being mainly produced by the macrophages localized in the aneurysm wall." (PMID 31963569, 2020). "Therefore, future working groups will need to investigate how, precisely, MMP-14 is regulated, as well as its activity in aTAA and role in MMP-2 activation at different stages of aneurysm development." (PMID 30794673, 2019). "Further studies should investigate whether there is a specific ratio at which MMP-2 activation exceeds the threshold of normal activation in healthy aortic tissue, that is, when aneurysm development is initiated." (PMID 30794673, 2019). "On the other hand, if our finding of lower TIMP-2 levels in aneurysm than in control tissue potentially indicates levels too low to activate MMP-2, those can be seen as a hypothesis-generating finding also." (PMID 30794673, 2019). "3-HAA was identified as a main factor in the pathomechanism of aneurysm development as it was found to upregulate the expression of matrix metallopeptidase 2 (MMP2), which has a central role in the pathophysiology of AAA formation via extracellular matrix degeneration." (PMID 31781097, 2019). "MMP9-/- and MMP2-/- mice were used to determine their effect on aneurysm formation." (PMID 31390798, 2019). "A similar function of MMP2 in migration and related proliferation of vascular smooth muscle cells during repair after vascular injury has also been demonstrated, along with a pathological role in models of aneurysm formation and atherosclerosis." (PMID 27996045, 2016). "Furthermore, tolylsam, a selective inhibitor of MMP-2, -9, and -12, reduced the progression of aneurysms to an advanced stage in the model." (PMID 25922566, 2015). "However, TIMP-2 in the aneurysm could be downregulated to increase MMP-2 activation, whereas TIMP-2's inhibitory function is predominant in controls." (PMID 30794673, 2019). "Furthermore, the aneurysm group's significant increase in active MMP-2 supports the hypothesis of increased proteolysis in the aneurysm, which could be a determining factor in the development and progression of aTAA." (PMID 30794673, 2019). "The central role of MMP-2 in aneurysm development is underlined by ROC analysis and the discrimination of aneurysmatic from control aortic tissue when active MMP-2 exceeds 10% compared to Pro-MMP-2 can be seen as a starting point for identifying aTAA biomarkers." (PMID 30794673, 2019). "Interestingly, a study using tissue biopsies from the UK Small Aneurysm Trial concluded that MMP-2 may only play an “etiopathogenic” role in small (<5.5 cm) aneurysms and moreover, significant quantities were bound to the ECM." (PMID 24028184, 2013). "Our group recently demonstrated that IFN‐γ stimulates the expression and activities of MMP‐2 and MMP‐9 in vivo and in vitro, leading to aneurysm formation." (PMID 40932621, 2025). "Specifically, MMP-2 and MMP-9 are prominent in aneurysms; MMP-9 is elevated in both TAAs and AAAs, as well as in Marfan syndrome, whereas MMP-2 is predominantly increased in AAAs." (PMID 41463310, 2025). "Elevated MMP activity, especially MMP-2 and MMP-9, is positively correlated with aneurysm diameter and severity, highlighting the importance of protease-mediated vascular remodeling." (PMID 40869102, 2025). "Upregulation of both MMP-2 and MMP-9, as well as of MMP-1, has been reported in aneurysms of the abdominal aorta." (PMID 39408865, 2024). "To determine if pyroptosis plays a role in human and mouse aneurysms, we evaluated markers of pyroptosis including NLRP3, CASP1, GSDMD and IL‐1β, and also analysed MMP2/9 in human aortic aneurysms and mouse AAA." (PMID 39601144, 2024). "Aortic VSMCs exposed to IL-1β, or TNF showed increased MMP2 or MMP9 activation mediated by a mechanism involving amplified ERK phosphorylation, thus promoting aneurysm progression." (PMID 39011492, 2024).
aneurysm (continued). "In BS, TNFα results in EC apoptosis and induces the expression of proinflammatory mediators, including metalloproteinases MMP-2 and MMP-9, which are important in ECM destruction and aneurysm formation." (PMID 36834577, 2023). "The matrix metalloproteinase (MMP) family, especially MMP-2 and MMP-9, is closely related to the destruction of ECM in aneurysm formation." (PMID 37175712, 2023). "The results of this study also confirmed that the expression and activity of MMP2 and MMP9 were significantly increased in the three groups of aneurysms." (PMID 35282381, 2022). "In their study, the interleukin-1beta (IL-1β), matrix metalloproteinase-2 and matrix metalloproteinase-9 (MMP-2, MMP-9), and nitric oxide synthetase (NOS) in aneurysm wall were all decreased compared to normal artery." (PMID 34847937, 2021). "Interestingly, early reports stated that the amount of infiltrated inflammatory cells positively correlates with the size of the aneurysm and an increased expression and activity of MMP-2 and MMP-9 may contribute to rapid AAA growth and rupture of larger aneurysms." (PMID 34572424, 2021). "With respect to abdominal aortic aneurysms, the gelatinases MMP-2 and MMP-9 have been found to be overexpressed in the aneurysm wall." (PMID 33573220, 2021). "MMP-2 expression in the tunica media was higher in MFS compared to non-MFS TAA (p < 0.05) and lower in control aortas compared to aneurysms (p < 0.05 and p < 0.01, respectively)." (PMID 32961817, 2020). "MMP-2 is increased in small aneurysms (<5.5 cm), whereas MMP-9 is dominant in large aneurysms (5.5–7 cm)." (PMID 31963569, 2020). "We suppose that increased collagen turnover results from the overactivity of metalloproteinases, possibly MMP2 and MMP3, both previously reported as crucial in the aneurysm formation." (PMID 32617140, 2020). "In the next step, we inspected the expression of other MMPs, MMP2 and MMP3, known to play a role in aortic wall degradation during aneurysm formation." (PMID 32617140, 2020). "Results from a murine aneurysm model suggested that TNF-α promotes MMP-2 and MMP-9 expression, increasing macrophage infiltration into the aortic tissue, thereby leading to aneurysm formation." (PMID 31989839, 2020). "In contrast, our analysis of the BAV group's zymographic data revealed significantly higher Pro-MMP-2 and total MMP-2 levels in the aneurysm's posterior part compared to its anterior part (p=0.007 versus p=0.002)." (PMID 33029391, 2020). "Regression analyses showed that only the p-values of the regression coefficients in aneurysms < 5.5 cm depicted a linear relationship between active MMP-2 and TIMP-2 (p = 0.002), as well as between active MMP-2 and MMP-14/TIMP-2 ratio (p = 0.024)." (PMID 30794673, 2019). "Trial dataindicate that both MMP-2 and MMP-9 should be available and active formaximum progression of the aneurysm, suggesting a synergistic andco-dependent relationship between no less than two of the most essentialproteases active in AAA disease." (PMID 28832801, 2017). "We found that these aneurysm prone factors significantly and concurrently induced HIF-1α, MMP-2 and MMP-9 expression (n = 4–5)." (PMID 27363580, 2016). "Since TIMP-4 is an important counter actor for MMP-2 in achieving a balanced matrix turnover, we assume that the observed difference in MMP-2/TIMP-4 ratio reflects this balance in our aneurysm patients." (PMID 26539497, 2015). "We found comparable collagen-stained area between the groups, significantly decreased mRNA level of CTGF, osteopontin-1, and MMP-2, and increased TIMP-4 expression in aneurysms." (PMID 26539497, 2015). "In this paper, we reported a cohort of patients diagnosed as intracranial aneurysms with obviously increase of SPARC, MMP2 and MMP9 in their pathological aneurysm tissue." (PMID 23516489, 2013).
aneurysm (continued). "We observed qualitatively the immunohistochemical staining of SPARC, MMP-2 and MMP-9 for each aneurysm and control artery and assigned each protein a grade ranging from negative staining to extensive staining in intimal and medial smooth muscle cells." (PMID 23516489, 2013). "The SPARC, MMP-2 and MMP-9 protein expression levels in aneurysms were investigated by immunohistochemistry, western blot and correlative analysis of their expression levels with clinicopathologic factors was performed." (PMID 23516489, 2013). "In the aneurysm group, both unruptured aneurysms (patients 1–4) and ruptured aneurysms (patients 5–31) exhibited moderate to extensive staining of medial smooth muscle cells for both SPARC and MMP-2/-9." (PMID 23516489, 2013). "MMP-2 is expressed in most cerebral aneurysms, whereas MMP-9 is expressed primarily in aneurysms with atherosclerotic changes." (PMID 22999528, 2012). "Moreover, Ang II-induced overexpression of critical genes involved in aneurysm pathogenesis—such as VEGF, MMP-2, MMP-9, HMGB1, and NF-κB p65—was significantly downregulated following CL treatment." (PMID 40868841, 2025). "Although MMP2 also plays a significant role in elastin degradation within aneurysms, tRF-AspGTC does not appear to be involved in the pathways regulating MMP2 expression and activation." (PMID 39776588, 2025). "However, after 7 days of healing, all humoral inflammation markers examined (TNF-α, IL6, MMP-2, MMP-9 and FGF) were markedly increased in coiled aneurysms." (PMID 37533024, 2023). "Whilst circulating levels of MMP-2 can readily be measured, they do not necessarily reflect local cellular concentrations, and hence correlation with aneurysm size is inappropriate." (PMID 35326494, 2022). "Notably, the levels of serum IL-1β and IL-1.ra were correlated with the relative levels of GSDMD, MMP2 and CD68 in aneurysm tissues." (PMID 35155635, 2022). "MMP2 and MMP9 are known to be pivotal in human aneurysm development." (PMID 33467682, 2021). "Between MMPs, MMP-2, -8, -9, and TIMP-1 are overexpressed and hyperactivated in the aneurysm wall." (PMID 33573220, 2021). "Our BAV Pro-MMP-2, total MMP-2, and TIMP-2 findings comparing the aneurysm's anterior and posterior parts concur with this hypothesis." (PMID 33029391, 2020). "In conclusion, MMP-2, MMP-9, and NGAL levels seem to play a major role in the development of aneurysms, and their levels are modulated by statin treatment, suggesting that HMG-CoA reductase inhibitors have a role in the prevention of these clinical manifestations." (PMID 32111073, 2020). "Samples taken fromaortic aneurysms demonstrate that MMP-2 activity is relatively lower thanthat of MMP-9, which suggests that expansion in MMP-2 activity could mean anearly event in the temporal evolution of AAA pathogenesis." (PMID 28832801, 2017). "Our previous study revealed that the inhibition of JNK could suppress the production of MMP-2 and MMP-9 in vitro; however, the relationship between JNK and MMPs in the nicotine-related aneurysm model remained unclear." (PMID 27688602, 2016). "We did not detect increase in MMP2 or MMP9 activity in total aneurysm medial tissue samples, whereas MMP-9 activity was significantly increased in SMCs and SMC culture media from aneurysm patients with both BAV and TAV." (PMID 26904289, 2016). "Significant increase of LDL, cholesterol, triglycerides and circulating inflammatory cells was observed in the Ang II-treated animals, and gene expression studies showed that ICAM-1, VCAM-1, MCP-1, M-CSF, MMP-2, MMP-9 and MMP-12 were upregulated in the aorta of aneurysm-induced mice." (PMID 23826202, 2013). "Increased levels of MMP-2, MMP-3, MMP-9 and MMP-12 have been identified in aneurysm vessel walls." (PMID 15482602, 2004).